ARG1 (arginase 1)
Diseases named in the same sentence as ARG1 in open-access papers (continued):
Sharing a sentence is not in itself a finding about the gene and the disease.
depression (15 papers, 2016 to 2025). "Conversely, enhancing IL-4 signaling to increase Arg-1+ microglia restored hippocampal neurogenesis and resistance to stress-induced depression." (PMID 37881439, 2023). "We continued to investigate the roles of Nrf2 and TREM2 levels and the microglial arginase 1+ phenotype in the mPFC in the context of depression-like behavior of CSDS mice." (PMID 36316319, 2022). "The knockout of Nrf2 decreases TREM2 and the microglial arginase 1+ phenotype in the mPFC of Nrf2 KO mice with depression-like behavior." (PMID 36316319, 2022). "Downregulating TREM2 expression decreases the microglial arginase 1+ phenotype in the mPFC, resulting in depression-like behavior in SFN-treated CSDS mice." (PMID 36316319, 2022). "The knockout of Nrf2 decreased TREM2 and arginase 1+ microglial phenotypes in the mPFC of Nrf2 KO mice with depression-like behavior." (PMID 36316319, 2022). "We confirmed that the M1 markers (IL-1β, IL-6, TNFα, iNOS, and CCL2) were induced and that the M2 molecules (Ym1, Arg1, IL-4, IL-10, and TGFβ) were impaired in depression." (PMID 27716270, 2016). "An animal study conducted in mice demonstrated that the reduction of arginase 1-positive microglia could potentially lead to anxiety/depression-like behavior through the decrease of pCREB/BDNF in Alzheimer’s Disease." (PMID 38794698, 2024). "Asperosaponin VI ameliorated depression-like behaviors of CMS mice based on SPT, TST and FST, and this was associated with a switch of hippocampal microglia from a pro-inflammatory (iNOS+-Iba1+) to neuroprotective (Arg-1+-Iba1+) phenotype." (PMID 35610721, 2022). "Finally, we identified ARG1, TPST1 and F5 as core genes associated with S100A12 expression in depression." (PMID 36325528, 2022). "The functional analysis of gene modules related to S100A12 also indicated that it may be involved in the immune regulatory response in depression, and the core genes of ARG1, TPST1 and F5 related to its expression were found." (PMID 36325528, 2022). "IL4‐driven microglia, characterized by high expression of Arg1, in the hippocampus trigger BDNF‐dependent neurogenesis, which is a response to chronic stress and a protection against depression‐like behaviors." (PMID 34878231, 2022). "The activation of Nrf2 by sulforaphane (Nrf2 activator) increases the microglial arginase 1+ phenotype by initiating TREM2 transcription in the medial prefrontal cortex (mPFC) and ameliorates depression-like behavior in CSDS mice." (PMID 36316319, 2022). "The activation of Nrf2 by SFN increased the microglial arginase 1+ phenotype by initiating TREM2 transcription in the medial prefrontal cortex (mPFC) and thus ameliorated depression-like behavior in CSDS mice." (PMID 36316319, 2022). "The protein levels of CX3CR1 and Arginase1 (Arg1), which were related to stress vulnerability and depression in our previous studies, were not changed in the hippocampus." (PMID 37396924, 2023). "Surprisingly, drug treatment reprogrammed Arg-1+ microglial cell phenotypes in the dentate gyrus region, suppressed neuronal inflammation, increased the quantification of hippocampal newborn neurons (BrdU+ - DCX+ cells), and improved depression-like behavior in CMS-exposed mice." (PMID 37881439, 2023).
liver fibrosis (15 papers, 2009 to 2025). "Arg1 can be associated with repair of the lung damage in response to damaging lung parasites like Nippostrongilus brasiliensis, liver fibrosis, and allergic airway inflammation." (PMID 40854598, 2025). "In a murine model of arsenic-induced liver fibrosis, the level of miR-21 and Arg-1 were increased; however, miR-21 deficiency in mice showed attenuated liver fibrosis and M2 polarization compared with WT mice exposed to arsenite." (PMID 37138859, 2023). "For example, the M1 subtype plays a role in killing schistosomula through NO production and preventing hepatic fibrosis, whereas the M2 subtype contributes to schistosome-induced hepatic fibrosis though Arg-1 metabolism of L-arginine to proline and polyamine." (PMID 34220800, 2021). "Arg1-expressing macrophages are known to inhibit liver fibrosis in mice." (PMID 27510556, 2016). "Thus, exposure of CD11b+-cells to EDA-FN increases arginase-1, resulting in diminished matrix accumulation in the liver and making this mechanism beneficial in liver fibrosis." (PMID 27653627, 2016). "Whether the increased L-arginine, which serves as a substrate for arginase-1, is also involved in alteration of liver fibrosis is still unclear and needs to be studied in animal models." (PMID 21978390, 2011). "Moreover, arginase-1 was highly expressed in infiltrated macrophages of infected Adrb2+/+ mice, indicating that the infiltrated macrophages involved in C. sinensis–induced liver fibrosis are AAMs (P<0.001)." (PMID 34733286, 2021). "Although early studies of schistosomiasis pathology indicate that M2 macrophage arginase 1 might contribute to liver fibrosis via production of proline as a precursor of collagen, mice lacking arginase 1 in macrophages display increased liver fibrosis and collagen deposition." (PMID 28223985, 2017). "Although Arg1 was hypothesized to be critical for collagen deposition, the Arg1−/flox;LysMcre mice showed no impairment in hepatic fibrosis at the acute stage of infection, and surprisingly, displayed marked and highly significant increases in fibrosis when chronically infected." (PMID 19360123, 2009).
allergic asthma (14 papers, 2011 to 2025). A asthma with a basis in a pathological type I hypersensitivity reaction. "Allergic asthma is associated with increased polarization of alveolar macrophages toward an M2 phenotype characterized by high arginase-1 expression levels [reviewed in Ref." (PMID 30147700, 2018). "In allergic asthma, Cloots and coworkers showed that mice genetically deficient for Arg1 displayed a reduction in Il4, Il5, Il13, Ccl2, and Ccl11, all Th2-related genes, suggesting that Arg1 may regulate type 2 inflammation." (PMID 34834178, 2021). "All these factors indicate the pathogenic roles of Arg1 in murine allergic asthma." (PMID 32024540, 2020). "Since the 20% remaining expression of Arg1 in the lungs of OVA/OVA-treated Arg1-KOLysM mediated an intermediate phenotype between OVA/OVA-treated Arg1-Con and Arg1-KOTie2Cre mice, we limited our description of the effects of pulmonary Arg1 deficiency on allergic asthma to Arg1-KOTie2Cre mice." (PMID 29183288, 2017). "The effects of elimination of NOS isoforms or arginase 1 on lung function and inflammation in mouse models of allergic asthma have been extensively investigated." (PMID 29792217, 2018). "Since the biology of female mice is underreported and since females are more often affected by allergic asthma than males, we compared the adaptive responses of Arg1-Con mice in both sexes." (PMID 29183288, 2017). "Arginase activity and arginase 1 expression are upregulated following environmental exposures in both sub-acute and chronic murine models of allergic asthma." (PMID 21291525, 2011). "The importance of IL-9-mediated Arg1+ macrophages in allergic asthma has been recently reported." (PMID 38162655, 2023). "Macrophage accumulation in the lung is characteristic of murine models of allergic asthma and the cells often bear the hallmarks of AAM/M(IL4)s (e.g. arginase-1+, FIZZ1+, Ym1+)." (PMID 34691050, 2021). "Expression of arginase I (Arg1) increases in murine models of allergic asthma induced by either OVA, A. fumigatis exposure, or house dust mite allergen (HDMA) (up to an 8-fold increase in total Arg1 expression in the airways of mice exposed to OVA)." (PMID 23554705, 2011). "In mouse models of allergic asthma, deletion of ARG1 did not have any effect in some studies but attenuated airway inflammation in female mice in other, indicating a gender difference." (PMID 38555460, 2024). "Also, we recommend selective suppression of pathogenic M2a proteins e.g. TGM2, CCL17/CCL22, TGF-β1, and murine Arg1, FIZZ1 and CHI3L3, for the future developments of effective therapies for allergic asthma." (PMID 32024540, 2020). "The hypothesis that the substantially increased expression of arginase 1 in activated macrophages limits the availability of L-arginine for nitric oxide synthesis, and thus increases AHR in lungs of mice with experimentally induced allergic asthma was recently refuted by several studies." (PMID 29792217, 2018).
helminth infections (14 papers, 2009 to 2024). "Arg1 expressing AAM are strongly associated with helminth infection, and are typically regarded as controlling inflammation and tissue repair rather than as protective immune cells." (PMID 24244174, 2013). "Arg1 expression during helminth infection is normally associated with an AAM phenotype dependent upon IL-4Rα signaling." (PMID 24244174, 2013). "The highly concentrated accumulation of Arginase-1 (Arg1) expressing alternatively activated macrophages in inflammatory lesions is a hallmark of type 2 responses associated with allergy or helminth infection." (PMID 24244174, 2013). "Therefore, although macrophage Arg1 expression is more commonly associated with AAMs found in helminth infections and allergic reactions, we discovered that CAMs also produce Arg1." (PMID 19360123, 2009). "Moreover, as helminth infections are known to induce markers associated with M2 in helminth infections, Pol-II occupancy was examined at the promoter regions of Arginase-1 (a signature marker of M2 activation phenotype)." (PMID 26148848, 2015). "During helminth infections, lamina propria macrophages produce various factors such as IL-4, IL-13, IL-10, arginase-1 (Arg-1), chitinase-like protein (Ym1), and resistin-like alpha." (PMID 38203591, 2023). "The elevated levels of arginase-1 in our studies are also indicative of the MΦ having an ‘alternatively activated’ phenotype which is a feature of many helminth infections." (PMID 19829705, 2009). "However, similar to the ability of IL-4 and IL-13 to induce the alternatively activated phenotype in macrophages in the context of helminth infections, fungus-induced Arg1 was also found to be at least partially dependent on IL-4Rα/STAT6." (PMID 21246055, 2011). "In contrast, AAMs, which are characterized by high expression of mannose receptor (also known as CD206), arginase-1 (Arg-1), Ym1, and Fizz1, generally exhibit anti-inflammatory properties and thus have the ability to suppress Th1-driven inflammatory pathology during helminth infections." (PMID 31727141, 2019). "It secretes anti‐inflammatory cytokines such as IL‐4, IL‐10 and transforming growth factor‐β (TGF‐β) and high expression of arginase 1 (Arg1) and mannose receptor (CD206), which play important roles in tissue repair, allergic inflammation and helminth infection." (PMID 37212362, 2023). "Reports of a regulatory macrophage phenotype in helminth infection or in response to helminth products suggest that this cell population is distinct from alternatively activated macrophages and in some cases it would appear to be independent of arginase-1." (PMID 27806135, 2016).
psoriasis (14 papers, 2014 to 2026). An autoimmune condition characterized by red, well-delineated plaques with silvery scales that are usually on the extensor surfaces and scalp. "Overproduction of ARG1 has been linked to keratinocytes overproducing NO in patients with psoriasis and basal carcinomas." (PMID 24936153, 2014). "In contrast, Arg1 overexpression was observed in lupus erythematosus, seborrheic dermatitis, and psoriasis due to the varying degrees of involvement in dysregulation of Th17/IL‐17A." (PMID 39665264, 2025). "Consistent with previous reports, we identified that Arg1 was overexpressed in the epidermis of psoriasis patients than healthy controls." (PMID 39665264, 2025). "We initially investigated the specific overexpression of Arg1 in psoriasis by examining patient samples with varied scaly erythematous skin diseases." (PMID 39665264, 2025). "Linear regression analysis demonstrated a positive correlation between Arg1 expression (H score) and with psoriasis area and severity index (PASI score), implying that Arg1 was involved in the psoriasis pathogenesis." (PMID 39665264, 2025). "In our study, we show that Arg1 is specifically overexpressed in psoriasis by analyzing skin and plasma samples from patients with scaly erythematous dermatosis." (PMID 39665264, 2025). "The combination of TNF‐α and IL‐17A has a pivotal role in the inflammatory cascade of psoriatic keratinocytes, where they activate the NF‐κB signaling pathway, leading to the overexpression of downstream genes, including Arg1 and psoriasis‐related genes." (PMID 39665264, 2025). "IL-17 downregulates protein phosphatase 6 (PP6) and induces the generation of arginase-1 (ARG1) in psoriasis." (PMID 37762693, 2023). "Polarized by Th2 cytokines (e.g., IL-4), M2 macrophages involved in anti-inflammation and repair process in psoriasis by secretion anti-inflammation cytokines (e.g., IL-10, Arg-1)." (PMID 33858431, 2021). "The dynamic changes in Arg1 for different groups strongly suggested that M-MDSC was involved in the pathogenesis of psoriasis." (PMID 33536902, 2020). "Overexpression of ARG1 is seen in significant proportion of psoriatic patients, and ARG1 inhibitors can be potentially used to treat psoriasis in those who overexpress." (PMID 32341806, 2020). "Together, these data demonstrated an inner link between Arg1 and innate immune cells (DCs) and adaptive immune cells (Th17), which might be IL‐17A secreted by DC/Th17A axis driving the Arg1 upregulation in psoriasis." (PMID 39665264, 2025). "We further investigated the expression of Arg1 in the epidermis of psoriasis mice by IHC." (PMID 39665264, 2025). "In psoriasis, the expression of ARG1 is increased and changed in its pattern within the epidermis." (PMID 41002986, 2025). "We also demonstrate the elevation of Arg1/polyamines could lead to the overactivation of the DCs/Th17 axis triggered by excess psoriasis‐specific self‐antigens." (PMID 39665264, 2025). "For instance, it is vital to prove that targeting Arg1‐mediated metabolic pathways to treat psoriasis is safe and superior to currently used clinical treatments that provide solutions not only to ameliorate but also to cure psoriasis." (PMID 39665264, 2025). "Together, targeting Arg1‐mediated polyamine production provides a novel strategy to interfere the DCs/Th17 axis and may offer therapeutic benefits for psoriasis therapy." (PMID 39665264, 2025). "Arg1 is overexpressed in the epidermis of psoriasis patients and correlates with disease severity." (PMID 40332512, 2025). "Additionally, an immunohistochemical analysis of Arg1 on skin sections from patients with scaly erythematous skin diseases similar to psoriasis was conducted." (PMID 39665264, 2025).
psoriasis (continued). "Moreover, an obviously improvement in M1-related inflammation medicators (TNF-α, IL-6, NO and iNOs) and suppression in M2-related anti-inflammation cytokines (IL-10 and Arg-1) emerged in psoriasis lesions in the skins of IMQ-treated mouse, which was consistent with previous reports." (PMID 33858431, 2021). "We found that the mRNA expression of Arg-1, TNF-α, ROR-γ, and PD-L1 was increased, while that of PD-1 and IL-10 mRNA was decreased in the PBMCs of psoriasis patients group." (PMID 32382290, 2020). "mRNA expression of Arg-1, TNF-α, PD-L1, and ROR-γ was increased, while the expression of PD-1 and IL-10 was decreased in the PBMCs of psoriasis patients." (PMID 32382290, 2020). "Compared with healthy controls, the mRNA expression of Arg-1, TNF-α, ROR-γ, and PD-L1 was increased, while the mRNA expression of PD-1 and IL-10 was decreased in PBMCs from psoriasis patients." (PMID 32382290, 2020). "Statistical analysis of qRT-PCR results indicated that the mRNA expression of Arg-1, TNF-α, PD-1, PD-L1, ROR-γ, and IL-10 in the PBMCs of psoriasis patient group was significantly different from expression levels of the control group." (PMID 32382290, 2020). "Unlike psoriasis, conditions such as parapsoriasis, atopic dermatitis, lichen planus, pityriasis rosea, and neurodermatitis have shown negligible Arg1 expression despite epidermis hyperplasia." (PMID 39665264, 2025). "Our results highlight the potential of targeting the Arg1/polyamine‐mediated DCs/Th17 axis by scavenging self‐antigens with nor@MSC‐EVs in clinically ameliorating psoriasis symptoms and providing an alternative for psoriasis therapy." (PMID 39665264, 2025). "Collectively, future studies and clinical trials using nor@MSC‐EVs for targeting Arg1 for evaluation of both efficacies and translational possibilities for the treatment of psoriasis may be warranted." (PMID 39665264, 2025). "The engineered nor@MSC-EVs inhibited the NF-κB pathway by targeting the Arg1/polyamine-mediated dendritic cells (DCs)/ T helper 17 (Th17) axis, reducing T helper 1 (Th1) and Th17 cell differentiation and alleviating skin lesions in a psoriasis mouse model." (PMID 40332512, 2025). "For example, one study loaded the Arginase-1 (Arg1) inhibitor nor-NOHA into MSC-EVs to create engineered nor@MSC-EVs and then evaluated their therapeutic effects in psoriasis." (PMID 40332512, 2025). "To address the metabolic and immunological disorder of psoriasis, we developed MSC‐EVs loaded with nor‐NOHA, an Arg1 inhibitor." (PMID 39665264, 2025).